PIEZO1 (piezo type mechanosensitive ion channel component 1 (Er blood group))
Diseases named in the same sentence as PIEZO1 in open-access papers (continued):
Sharing a sentence is not in itself a finding about the gene and the disease.
cardiac hypertrophy (19 papers, 2018 to 2025). "Consistent with this hypothesis, a transgenic mouse model overexpressing Piezo1 displayed cardiac hypertrophy and myocardial fibrosis that were associated with a significant increase in Piezo1-mediated Ca2+ signals in cardiac fibroblasts." (PMID 40149710, 2025). "Furthermore, PIEZO1 expression is upregulated during cardiac insult—i.e., in cardiac hypertrophy and HF—and the loss of cardiomyocyte PIEZO1 inhibits adverse remodelling caused by aortic banding in mice." (PMID 35406763, 2022). "The previously reported PIEZO1 M2241R GOF variant, which causes mild cardiac hypertrophy and fibrosis in homozygous mice, provides an important comparison point." (PMID 41237237, 2025). "In recent years, targeted interventions against Piezo1 have shown promising results in animal models of myocardial hypertrophy and heart failure." (PMID 41195420, 2025). "The cardiac hypertrophy induced by Piezo1 activation was mediated by Ca2+-related calcineurin and Calpain activation." (PMID 40857264, 2025). "Piezo1 is known to act together with other TRP channels: in response to pressure overload, Piezo1 transduces mechanical signals to TRPM4 channels in cardiac hypertrophy, and Piezo1 cooperates with TRPV4 channels in pressure-induced pancreatitis." (PMID 40019468, 2025). "Studies have shown that the use of Piezo1 inhibitors can significantly alleviate pressure overload-induced myocardial hypertrophy, reduce heart weight, and improve both ventricular systolic function and diastolic compliance." (PMID 41195420, 2025). "Conditional deletion of Piezo1 attenuated the effects of isoproterenol-induced myocardial hypertrophy in mice by reducing Ca2+ overload and Calpain activity." (PMID 40857264, 2025). "This increased IL-6, which was reported by the same group to contribute to cardiac hypertrophy, was reduced in fibroblasts-transfected with Piezo1-specific siRNA, highlighting the pivotal role of this channel." (PMID 35897650, 2022). "Looking ahead, research on Piezo1 in cardiac diseases extends beyond pathological myocardial hypertrophy and heart failure and may also relate to cardiac regeneration, metabolic remodeling, and arrhythmias." (PMID 41195420, 2025). "Interestingly, it was recently shown that Piezo1 in the mouse heart is a mechanosensor responsible for the development of cardiac hypertrophy under pressure-overload conditions." (PMID 40724903, 2025). "In contrast, PIEZO1 activated calpain/calcineurin signaling to promote cardiac hypertrophy, and calcineurin could bind and dephosphorylate TFEB, thereby promoting its nuclear translocation." (PMID 37485782, 2024). "During cardiac hypertrophy, relative expression of the two isoforms is reversed, consistent with the increased β-MHC mRNA expression we observed in our model of the human M2225R PIEZO1 mutation." (PMID 35406763, 2022). "However, further studies are required to investigate the close interaction of TRPV4 with Piezo1 in pathological cardiac hypertrophy." (PMID 35731090, 2022). "Moreover, they demonstrated an attenuated progression of the pathological cardiac hypertrophy in cardiac-specific Piezo1 knockdown mice and in cardiomyocytes, but also a reduction in fibrotic remodeling." (PMID 35897650, 2022). "Mechanosignaling involving Piezo1 ion channels in the function of the heart and cardiovascular system has only recently been identified to have implications for cardiovascular physiology and pathophysiology, in particular for heart failure (i.e., hypertrophy or dilative cardiomyopathy)." (PMID 38485771, 2024). "In HCFBs and MCFBs, PIEZO1 activated by Yoda1 mediates Ca2+ inward flow and intracellular Ca2+ is involved in the p38MAPK/IL-6 pathway of myocardial hypertrophy and fibrosis, but this pathway may be influenced by the matrix or tissue stiffness surrounding PIEZO1." (PMID 39272994, 2024).
cardiac hypertrophy (continued). "Study on the role of Piezo1 in cardiomyocytes is lacking; however, mechanical stretch was shown to increase cardiac hypertrophy in mice that expressed the stretch-responsive G-protein-coupled receptor, APJ." (PMID 30400259, 2018). "In cardiac cells, the Piezo1 activity does not contribute much to the basal Ca2+ level, but upon mechanical or chemical stimulation, it elicits Ca2+-mediated calpain and calcineurin activation, responsible for the cardiac hypertrophy." (PMID 35743058, 2022). "Thus, the finding of a similar interaction between Piezo1 and TRPM4 opens an attractive possibility of developing novel compounds targeting specifically the Piezo1/TRPM4 interface for treatment of cardiac hypertrophy and possibly other cardiac mechanochannelopathies." (PMID 40869375, 2025).
prostate carcinoma (19 papers, 2021 to 2026). A carcinoma that arises from epithelial cells of the prostate gland. "In prostate cancer cells, a similar effect was seen where Piezo1 knockdown caused a small reduction in cell viability in vitro in DU145 cells." (PMID 34831037, 2021). "Piezo1 has also been linked to increased cancer cell survival in gastric and prostate cancer." (PMID 34831037, 2021). "Prostate cancer is one of the most common cancers in men, and the expression level of the Piezo1 channel in human prostate cancer is significantly higher than that in non-malignant tissues." (PMID 38690080, 2024). "Our first model system confirmed that the pro-apoptotic effects of TRAIL therapeutics in prostate cancer cells can be enhanced via FSS-induced Piezo1 activation." (PMID 38824207, 2024). "Shear stress enhances Piezo1 activity in prostatic cancer cells, leading to Src/YAP signaling activation and prostate tumor progression." (PMID 37762011, 2023). "Immunohistochemistry analysis of malignant and benign prostate cancer tissues shows that Piezo1 is elevated with disease progression." (PMID 36158191, 2022). "Akt and mTOR are activated and mediate Piezo1 activity, which promotes cell cycle progression in prostate cancer cells." (PMID 35163745, 2022). "Downregulating Piezo1 through shRNA or GsMTx4 in prostate cancer results in the inhibition of migration." (PMID 35884459, 2022). "For example, downregulation of Piezo1 reduces cell viability and proliferation in prostate cancer cells, arresting cells in the G0/G1 phase of the cell cycle." (PMID 35884459, 2022). "Accordingly, Piezo1 downregulation in human prostate cancer (DU145) cells reduces proliferation and migration in vitro and tumor growth in vivo." (PMID 36158191, 2022). "A study of Piezo1 in prostate cancer showed that shRNA knockdown of Piezo1 significantly reduced proliferation and caused cell-cycle arrest by reducing the activity of Akt/mTOR in a calcium-mediated process." (PMID 34831037, 2021). "In prostate cancer cells, Piezo1 activation by fluid shear stress and Yoda1 significantly increased the sensitivity of the cells to TRAIL-mediated apoptosis." (PMID 34831037, 2021). "Piezo1 activation promotes migration in breast, gastric, colorectal, pancreatic, and prostate cancer cells." (PMID 34831037, 2021). "When Piezo1 is activated, calcium flow can be increased to further activate the Akt/mTOR signaling pathway, leading to Akt/mTOR phosphorylation, which promotes the proliferation and migration of prostate cancer cells and the growth of prostate tumors." (PMID 38690080, 2024). "Similarly, in vitro experiments, Piezo1 downregulation induced reduced migration of prostate cancer cells by inhibiting Akt and mTOR phosphorylation." (PMID 38690080, 2024). "Downregulation of Piezo1 in prostate cancer cells cultured in vitro could inhibit the cells’ migration." (PMID 39451215, 2024). "Moreover, there is experimental evidence that knocking out the Piezo1 channel can lead to reduced proliferation and migration of prostate cancer cells, indicating the anti-proliferative effect of Piezo1 knocking out." (PMID 38690080, 2024). "Similarly, Piezo1 is also overexpressed in prostate cancer cells compared to normal tissue, and its upregulation leads to Akt/mTOR activation, promoting cell cycle progression and, subsequently, prostate tumor growth." (PMID 37762011, 2023). "Furthermore, Piezo1 is known to mediate prostate cancer cell proliferation and migration via AKT/mTOR signaling." (PMID 37306789, 2023). "Piezo1 has not been directly associated with colonization; however, increased intraosseous pressure has been shown to promote colonization of the bone by prostate cancer cells." (PMID 36837670, 2023). "Piezo1 is highly expressed in the cytoplasm of human prostate carcinoma tissue." (PMID 35461277, 2022). "Piezo1 expression is elevated in human prostate cancer tissues and cell lines." (PMID 35163745, 2022).
prostate carcinoma (continued). "Interestingly, the present study demonstrated that Piezo1 regulation of the cell cycle in prostate cancer cells is associated with the Akt/mTOR pathway, but not with the ERK1/2 pathway." (PMID 38690080, 2024). "Piezo1 has been shown to sensitize PC3 prostate cancer cells to TRAIL via the intrinsic apoptotic pathway, where Ca2+ activates calpain via Piezo1, subsequently amplifying death-inducing signals in the TRAIL-mediated apoptotic pathway." (PMID 40061015, 2025). "Piezo1 can sense the change in ECM stiffness and regulate the content of ECM markers by regulating calcium flux, which plays an important role in prostate cancer cell metastasis and extravasation." (PMID 38690080, 2024). "Similarly, a study on prostate cancer showed that Piezo1 downregulation inhibited the expression of Cyclin D1 and CDK4, hindering the assembly of the Cyclin D1-CDK4 complex and thus impeding cell cycle progression in prostate cancer cells." (PMID 38690080, 2024). "Besides, fluid shear stress and Yoda1 synergistically activate Piezo1 in prostate cancer cells by increasing the proportion of early S/S/G2/M phase in the cell cycle through the activation of YAP/TAZ, while transplanted Piezo1-silenced prostate cancer cells failed to proliferate in vivo (Kim O-H." (PMID 38690080, 2024).
pulmonary fibrosis (18 papers, 2021 to 2026). Chronic progressive interstitial lung disorder characterized by the replacement of the lung tissue by connective tissue, leading to progressive dyspnea, respiratory failure, or right heart failure. "Experimental studies have demonstrated that Piezo1 has an active role in ARDS-associated pulmonary fibrosis exacerbated by mechanical stretch (MV) via mediation of calcium inward flow as well as ATP emission." (PMID 37900917, 2023). "Notably, as suggested by our cytokine antibody arrays, levels of CCL24 (also known as eotaxin-2), a chemokine strongly associated with dermal and pulmonary fibrosis, were lower in Piezo1 knockdown HDFs grown on higher substrate stiffness." (PMID 38267432, 2024). "In summary, we demonstrate that the Postn+ myofibroblasts drive lung fibrosis and PIEZO1-mediated mechanosensation essential for myofibroblast activation and the development of lung fibrosis." (PMID 40454481, 2025). "Conditional Piezo1 deletion or pharmacological PIEZO1 inhibition in myofibroblasts dramatically improved lung fibrosis by suppressing myofibroblasts activation and proliferation." (PMID 40454481, 2025). "Linked to these findings, we generated the Postn-CreERT2; Piezo1fl/fl; mT/mG mice to simultaneously target PIEZO1 in myofibroblasts and trace its fate during the course of lung fibrosis." (PMID 40454481, 2025). "Activation of PIEZO1 in monocytes has been related to increased proinflammatory gene expression in lung infection, sepsis, pulmonary fibrosis, and renal fibrosis." (PMID 40454475, 2025). "PIEZO1 plays a vital role in the mechano-activation of Postn+ myofibroblast during the development of lung fibrosis." (PMID 40454481, 2025). "Genetic or pharmacological inhibition of PIEZO1 attenuated these effects, highlighting its potential as a therapeutic target in critical care and pulmonary fibrosis." (PMID 40863236, 2025). "The mechanosensitive Hippo-YAP/TAZ pathway is widely implicated in the pathogenesis of organ fibrosis, and our data suggest that PIEZO1-induced YAP/TAZ signaling drives myofibroblast activation in pulmonary fibrosis." (PMID 40454481, 2025). "Consistently, Piezo1 deletion with Col1a2-CreERT2, a cre line mainly targeting fibroblast-traced myofibroblasts, also moderately attenuated bleomycin-induced lung fibrosis." (PMID 40454481, 2025). "We discovered that the mechanosensitive cation channel PIEZO1 is highly expressed in Postn+ cells and plays a vital role in the mechanoactivation of Postn+ cells and lung fibrosis." (PMID 40454481, 2025). "PIEZO1 was highly expressed in Postn+ myofibroblast and played a vital role in mechanoactivation of Postn+ myofibroblast and development of lung fibrosis." (PMID 40454481, 2025). "Conditional deletion of Piezo1 in Postn+ myofibroblasts significantly inhibited lung fibrosis by suppressing myofibroblast activation and proliferation." (PMID 40454481, 2025). "Conditional Piezo1 deletion or pharmacological PIEZO1 inhibition in myofibroblasts dramatically improved lung fibrosis." (PMID 40454481, 2025). "Previous studies demonstrated that upregulation of Piezo1 was associated with an increase in lung vascular hyperpermeability, pulmonary hypertension and ARDS-associated pulmonary fibrosis." (PMID 38303078, 2024). "Research with a two-hit model indicated that mechanical stretching exacerbated the hydrochloric acid-induced lung injury and enhanced pulmonary fibrosis, which was driven by Piezo1-mediated ATP release in AECs." (PMID 39664395, 2024). "Although Piezo1-mediated ATP release is essential in the exacerbation of pulmonary fibrosis by mechanical stretch, the association of ATP with EMT and pulmonary fibrosis remains to be investigated." (PMID 37900917, 2023). "Piezo1 is also an upstream modulator of the RhoA/Rock1 pathway, activating this signaling pathway and inducing the onset of pulmonary fibrosis." (PMID 37900917, 2023).
pulmonary fibrosis (continued). "In this review, we are focusing on Piezo1 and its potential contribution to the pathophysiology of pulmonary fibrosis, renal fibrosis, pancreatic fibrosis, and cardiac fibrosis diseases." (PMID 37900917, 2023). "Knockout of the Piezo1 gene in mice has a protective effect on pulmonary fibrosis induced by bleomycin." (PMID 35154133, 2022). "There is also emerging evidence that implicates a role for PIEZO1 in exacerbating lung diseases, as PIEZO1 in macrophages drives autoinflammatory disease pathology in a bleomycin-induced pulmonary fibrosis model." (PMID 36467420, 2022). "Knockdown of Piezo1 partially reversed radiation-induced in vitro epithelial-mesenchymal transition and played a therapeutic role in bleomycin-induced pulmonary fibrosis in rats." (PMID 35154133, 2022). "Piezo1 signaling in myeloid cells also exacerbated a mouse model of pulmonary fibrosis; thus, it appears that Piezo1 can induce fibrosis by acting both directly on stellate cells and indirectly through inflammatory cells." (PMID 35451372, 2022). "Piezo1 signaling in myeloid cells exacerbates pulmonary fibrosis, suggesting that mechanosensation in the altered microenvironment of fibrotic tissue can itself trigger auto-inflammation." (PMID 35906615, 2022). "Piezo1 responds to lung mechanical stress and is involved in the development of pulmonary fibrosis through multiple mechanisms." (PMID 35154133, 2022). "It has been suggested that PIEZO1 in myeloid cells plays an important role in the process of bleomycin-induced pulmonary fibrosis by promoting autoinflammatory processes." (PMID 34722630, 2021). "PIEZO1, a mechanosensitive calcium channel, is expressed in myeloid cell and has been found to play an important role in bleomycin-induced pulmonary fibrosis." (PMID 34722630, 2021). "Additionally, using a co-culture system, we showed that PIEZO1-induced NETosis exacerbates pulmonary fibrosis in lung epithelial cells." (PMID 41880127, 2026). "Thus, Postn labels pulmonary myofibroblasts and PIEZO1 plays a vital role in the mechano-activation of Postn+ myofibroblasts during the development of lung fibrosis." (PMID 40454481, 2025). "However, little is known about the expression and function of PIEZO1 in myofibroblasts and its contribution to pulmonary fibrosis." (PMID 40454481, 2025). "PIEZO1 promotes myofibroblast activation and lung fibrosis via YAP/TAZ." (PMID 40454481, 2025). "Deletion of Piezo1 in Postn+ cells strongly reduced bleomycin-induced pulmonary fibrosis." (PMID 40454481, 2025). "Additionally, pharmacological inhibition of Piezo1 with GsMTx4 alleviated lung pathological changes, water content and protein leakage in the process of MV-exacerbated ARDS-associated pulmonary fibrosis." (PMID 38303078, 2024). "In pulmonary fibrosis, the upregulation of Piezo1 is an important event, which may serve as a response to mechanical stimuli and play a key role in the occurrence and progression of fibrosis." (PMID 37900917, 2023). "However, the effects of Piezo1 on inflammation are complex: While Piezo1 activation is protective against bacteria infection, deletion of Piezo1 is also protective in a mouse model of pulmonary fibrosis." (PMID 36177027, 2022). "Given the importance of the Piezo1 channel in lung disease, it is reasonable to ask whether mammalian Piezo1 plays a role in other lung diseases, such as chronic obstructive pulmonary disease, asthma, and mechanical stretch-induced pulmonary fibrosis." (PMID 33422128, 2021). "Piezo1 is a mechanosensitive calcium channel, and immunohistochemical staining revealed widespread Piezo1 expression in mouse pulmonary tissues, epithelial cells, and endothelial cells, and was suggested to play an important role in bleomycin-induced pulmonary fibrosis." (PMID 37900917, 2023).
pulmonary fibrosis (continued). "Moreover, authors used bleomycin-induced pulmonary fibrosis model to investigate if Piezo1 in myeloid cell could drive autoinflammatory disease and found that there was lower level of lung damage in Piezo1ΔLysM mice." (PMID 35906615, 2022). "However, whether there is a role of AT II cell PIEZO1 in pulmonary fibrosis, especially radiation-induced EMT and fibrosis is unclear." (PMID 34722630, 2021). "Accordingly, targeting Piezo1 and its downstream pathways is regarded as a highly promising EMT-oriented therapy for ventilation-related and other stress-induced pulmonary fibrosis." (PMID 40988754, 2025). "Evidence indicates that Piezo1 amplifies EMT by inducing Ca2+ influx and co-activating RhoA/ROCK1 and p38-MAPK pathways, culminating in collagen deposition and pulmonary fibrosis." (PMID 40988754, 2025). "Mechanical stretch activates Piezo1, leading to Ca2+ influx, activating the Ca2+/HIF-1α signaling pathway of TGF-β1, inducing epithelial-mesenchymal transition (EMT), and promoting pulmonary fibrosis." (PMID 37900917, 2023). "Piezo1 is activated in response to cyclic pressure and drives c-JUN activation, endothelin-1 overexpression and HIF1α stabilization, facilitating the pro-inflammatory program in mouse lung fibrosis." (PMID 38267432, 2024). "Piezo1 can induce ATP release during the mechanical stretch, and the released ATP can, in turn, drive mechanical stretch to enhance EMT, thus exacerbating pulmonary fibrosis, and leading to more severe pulmonary fibrosis in ARDS during ventilation." (PMID 37900917, 2023). "PIEZO1 plays a crosstalk role between TGFβ and EMT, which implicates that PIEZO1 may be a target for the treatment of EMT-related diseases including radiation-induced pulmonary injury (RIPI) and pulmonary fibrosis." (PMID 34722630, 2021). "However, it is not known whether PIEZO1 is expressed and functional in myofibroblasts in lung fibrosis." (PMID 40454481, 2025).